S100B (S100 calcium binding protein B)
Diseases named in the same sentence as S100B in open-access papers (continued):
Sharing a sentence is not in itself a finding about the gene and the disease.
Cirrhosis (1 paper, 2022). A chronic disorder of the liver in which liver tissue becomes scarred and is partially replaced by regenerative nodules and fibrotic tissue resulting in loss of liver function. "Another study showed that compared with 13 cirrhosis patients without HE and 8 healthy subjects, blood levels of S100b in most of the 35 ALF patients studied were increased but unrelated to the survival rate." (PMID 35911735, 2022).
clostridium difficile infection (1 paper, 2023). Symptomatic infection due to the spore-forming bacterium clostridium difficile. "For example, in Clostridium difficile infection, S100β activates the RAGE/phosphoinositide 3-kinase (PI3K)/NF-κB pathway, causing an increase in IL-6 expression, leading to IEB damage and intestinal inflammation." (PMID 37779161, 2023).
coronary atherosclerosis (1 paper, 2023). Atherosclerosis of the coronary vasculature. "Moreover, RPS3A, BCL6, and S100B play a critical role in coronary atherosclerosis." (PMID 37316908, 2023).
coronary heart disease (1 paper, 2015). "We aimed to evaluate serum levels of S-100 beta (S-100β) and neuron specific enolase (NSE) in patients with coronary heart disease (CHD) after off-pump versus on-pump coronary artery bypass graft (CABG) surgery." (PMID 26179379, 2015).
Duchenne muscular dystrophy (1 paper, 2017). Duchenne muscular dystrophy (DMD) is a neuromuscular disease characterized by rapidly progressive muscle weakness and wasting due to degeneration of skeletal, smooth and cardiac muscle. "Interestingly, S100B is released in high abundance from degenerating muscles of mdx mice, an animal model of Duchenne muscular dystrophy (DMD), and blocking S100B ameliorates histopathology." (PMID 28970581, 2017).
edema (1 paper, 2023). An abnormal accumulation of fluid beneath the skin, or in one or more cavities of the body. "A model was derived for early predicting malignant cerebral edema, including S100B protein and IL-1 beta." (PMID 37752283, 2023).
encephalomyelitis (1 paper, 2021). Inflammation of the brain and the spinal cord. "Brain damage marker S-100B and C reactive protein increased before symptoms or signs of encephalomyelitis and peaked when the patient fell into a coma." (PMID 34215689, 2021).
endometrial cancer (1 paper, 2023). Primary or metastatic malignant neoplasm involving the endometrium (mucous membrane that lines the endometrial cavity). "In addition, we found that low-grade endometrial cancer-draining LNs showed lower S100A/S100B MDSCs and CD163 macrophages than high-grade tumors, with no other significant differences, suggesting a more immunocompetent LN milieu in low-grade tumors." (PMID 36835583, 2023).
esophageal squamous cell carcinoma (1 paper, 2021). Esophageal squamous cell carcinoma (ESCC) is a type of esophageal carcinoma (EC) that can affect any part of the esophagus, but is usually located in the upper or middle third.
falciparum malaria (1 paper, 2022). "Patients with SNCM had a significantly higher levels of S100B than patients with UM (P = .0002), confirming a degree of brain injury in patients with severe falciparum malaria with or without mildly decreased GCS scores." (PMID 34905777, 2022).
fibrosarcoma (1 paper, 2021). A malignant mesenchymal fibroblastic neoplasm affecting the soft tissue and bone. "The tumor lacked the herringbone pattern characteristic of an adult-type fibrosarcoma; the presence of S100β immunoreactivity was also inconsistent with this diagnosis." (PMID 33707600, 2021).
hypothyroidism (1 paper, 2023). Abnormally low levels of thyroid hormone. "A positive, strong correlation was observed with metformin treatment, whereas other parameters showed moderate (TG, insulin, BMI, waist circumference, S100B, and LEP) and weak (hypothyroidism and VIS_E) positive correlation." (PMID 37960185, 2023). "Seven of the examined variables (hypothyroidism, waist circumference, HDL, ADIPO, S100B, LEP, and LEP_R) correlated with sex; therefore, we decided to study women and men groups separately." (PMID 37960185, 2023).
ileitis (1 paper, 2017). "As a matter of fact, we observed increases in GFAP- and S100β-immunoreactivities in TNBS-induced ileitis suggesting that the inflammatory insult may stimulate enteric glial cells proliferation and/or activate the expression/synthesis of glial protein cell markers." (PMID 29167643, 2017).
infantile neuronal ceroid lipofuscinosis (1 paper, 2016). A form of neuronal ceroid lipofuscinosis (NCL) characterized by onset during the second half of the first year of life and rapid mental and motor deterioration leading to loss of all psychomotor abilities. "Moreover, S100B production and subsequent RAGE expression can lead to neuronal apoptosis mediated by ER-stress in infantile neuronal ceroid lipofuscinosis (INCL) and palmitoyl-protein thioesterase-1- (PPT1-) KO mice." (PMID 27313835, 2016).
Intervertebral Disk Disease (1 paper, 2013). "The aim of the study was to investigate S100β levels in the cerebrospinal fluid of nonambulatory dogs with intervertebral disk disease treated with electroacupuncture:10 dogs with thoracolumbar disk extrusion graded 3 to 5 (EA group) and 7 dogs without neurologic dysfunction (control group)." (PMID 26464906, 2013).
Krabbe disease (1 paper, 2022). A lysosomal disorder that affects the white matter of the central and peripheral nervous systems. "iPSCs from three healthy controls and two donors with infantile onset Krabbe disease successfully differentiated into astrocytes that expressed appropriate lineage markers vimentin, S100β, CD44, and GLAST." (PMID 35921286, 2022).
leiomyosarcoma (1 paper, 2021). An uncommon, aggressive malignant smooth muscle neoplasm, usually occurring in post-menopausal women. "Further, although occasional leiomyosarcomas are immunoreactive for S100β, this tumor was negative for desmin, which ruled out this diagnostic possibility." (PMID 33707600, 2021).
liver cancer (1 paper, 2022). An epithelial or non-epithelial malignant neoplasm that arises from the liver. "Further regression analysis using cBioPortal revealed that S100B mRNA level was positively correlated with HIF-1α expression in liver cancer." (PMID 35368338, 2022). "Therefore, we focused on the functions of S100B in hypoxia responses and immune related signaling pathways in liver cancer." (PMID 35368338, 2022). "However, studies of the association of S100B with liver cancer incidence have not been reported so far." (PMID 35368338, 2022). "Moreover, combination of immunotherapies with S100B inhibitors may be helpful for the effective targeted therapy of liver cancer." (PMID 35368338, 2022).
liver failure (1 paper, 2023). A liver disease characterized by the liver losing or has lost all of its function. "Hepatic stellate cells, which share many functional and morphologic characteristics with glial cells, were suggested as another relevant source of serum S100B in the setting of liver failure." (PMID 36766438, 2023).
liver fibrosis (1 paper, 2023). "In our previous experimental study, we found that hepatic stellate cells, the key players in liver fibrosis, are activated by recombinant S100B protein treatment." (PMID 36766438, 2023).
macrosomia (1 paper, 2022). "In particular: (i) S100B can be released as a neurotrophic factor contributing to macrosomia." (PMID 35162052, 2022).
malnutrition (1 paper, 2010). Inadequate nutrition resulting from poor diet, malabsorption, or abnormal nutrient distribution. "Thus, glial cells, mainly producing S100B, remain unaffected by malnutrition." (PMID 20614004, 2010).
metastasis (1 paper, 2012). The spread or migration of cancer cells from one part of the body (where they first appeared) to another. "In Taiwanese CRC patients, liver metastasis is correlated with S100B overexpression." (PMID 23166536, 2012).
middle ear cholesteatoma (1 paper, 2018). "Cells expressing the “stemness” markers Nestin and S100B were detected in middle ear cholesteatoma and auditory canal skin." (PMID 29670222, 2018).
obsessive-compulsive disorder (1 paper, 2014). A disorder characterized by the presence of persistent and recurrent irrational thoughts (obsessions), resulting in marked anxiety and repetitive excessive behaviors (compulsions) as a way to try to decrease that anxiety. "Serum BDNF (log) was inversely associated with PPT (log) (β = -1.01, SE = 0.41), age (β = -0.02, SE = 0.15) and obsessive compulsive disorder (β = -0.36, SE = 0.15), while serum S100B (log) was inversely associated with PPT (log) (β = -1.38, SE = 0.50), only." (PMID 25005881, 2014). "Variables that were independently correlated with BDNF (log) and S100B (log) significant in the multiple linear regression models included age, log PPT and obsessive compulsive disorder according to the MINI." (PMID 25005881, 2014).
organophosphate poisoning (1 paper, 2023). Poisoning due to organophosphates (a class of organophosphorus compounds also known as phosphate esters, or OPEs). "The role of S100B is a predictor of neurologic complications in patients with organophosphate poisoning; serum S100B was higher in patients than in the control group." (PMID 37713081, 2023).
osteoarthritis (1 paper, 2021). A noninflammatory degenerative joint disease occurring chiefly in older persons, characterized by degeneration of the articular cartilage, hypertrophy of bone at the margins and changes in the synovial membrane. "S100B could participate in the FGFR1-mediated inflammatory response in osteoarthritis." (PMID 34250093, 2021).
osteosarcoma (1 paper, 2014). A usually aggressive malignant bone-forming mesenchymal neoplasm, predominantly affecting adolescents and young adults. "To investigate the regulation of S100B by SOX10 in Schwann cells, we retrovirally overexpressed SOX10 in primary rat sciatic Schwann cells and rat osteosarcoma ROS cells (top)." (PMID 25536222, 2014).
panic disorder (1 paper, 2023). An anxiety disorder characterized by multiple unexpected panic attacks with persistent concern of recurring attacks. "Similar S100B levels were found in MDD and panic disorder patients." (PMID 37759935, 2023).
peripheral nerve injuries (1 paper, 2023). "Comparing the sources of equine MSCs subjected to the induction medium, we observed that the gene expression of GFAP and S100β was significantly higher in equine AT-MSCs, which is the best candidate for cell-based therapy in the context of peripheral nerve injuries." (PMID 37071193, 2023).
primary progressive MS (1 paper, 2004). "The key questions were whether S100B levels were associated with either disability or MRI findings in primary progressive MS and whether Interferon β-1a has an effect on their S100B levels." (PMID 15482599, 2004). "In this clinically negative phase II study, we assessed the effect of IFNβ-1a on serum levels of S100B at 3-month intervals in subjects with primary progressive MS (PPMS)." (PMID 15482599, 2004). "The results demonstrated that serum S100B is not related to either disease progression or MRI findings in subjects with primary progressive MS given Interferon β-1a." (PMID 15482599, 2004).
prostatic adenocarcinoma (1 paper, 2004). "In neuronal cell lines it has been shown that S100B may form heterodimers with S100A6 and that S100B protein expression is co-localised with S100A6, we therefore performed immunostaining for S100B in 20 cases of organ confined prostatic adenocarcinoma with adjacent benign epithelium." (PMID 15280928, 2004).
pulmonary emphysema (1 paper, 2024). A subcategory of chronic obstructive pulmonary disease (COPD). "Statistical analysis revealed a significant correlation between S100β and Hps70 immunoexpression and cerebral pathological features, between ICAM-1 immunoexpression and alveolar edema and pulmonary emphysema, and between AQP-1 immunoexpression and pulmonary emphysema." (PMID 38611652, 2024).
respiratory infections (1 paper, 2025). "The S100 protein family, which includes members such as S100A4, S100A8, S100A9, S100A12, S100B, and S100P, is known to participate in inflammatory processes and has been implicated in various disease states, including respiratory infections." (PMID 41585373, 2025).
retinal ischemia (1 paper, 2023). A ischemic disease that involves the retina. "Furthermore, the S100B glial marker, overexpressed after retinal ischemia, was attenuated by fluoxetine treatment." (PMID 37242611, 2023).
Senile plaques (1 paper, 2019). Senile plaques are extracellular deposits of amyloid in the gray matter of the brain. "It was also observed that S100B positive astrocytes are present in the diffuse non-neuritic amyloid plaques, suggesting an early, yet unclear, action of S100B in the formation of senile plaques." (PMID 31156365, 2019).
serous ovarian cancer (1 paper, 2018). "S100A4, S100B, S100A14, S100P expressions are associated with poor prognosis, moreover,high cytoplasmic S100A10 staining is significantly associated with reduced overall survival (OS) and progression-free survival (PFS) in serous ovarian cancer." (PMID 30558666, 2018).
spina bifida (1 paper, 2022). A congenital neural tube defect in which vertebrae are not fully formed. "Our results further support this evidence as Sox9, Notch1, and BMP2/4 gene expression was upregulated at the time of early astrogliosis in spina bifida, and BMP2/4 expression with S100b and Aldh1l1, an early astrocyte markers." (PMID 35782393, 2022).
spinal muscular atrophy (1 paper, 2021). A motor neuron disease that affect the muscles, and characterized by muscle weakness and atrophy resulting from progressive degeneration and irreversible loss of the anterior horn cells in the spinal cord (i.e., lower motor neurons) and the brain stem nuclei. "The interaction with NCALD is also likely to mediate trafficking of S100B in response to calcium both in glia and neurons: NCALD is known to bind to cytoskeletal elements and clathrin and regulate endocytosis in spinal muscular atrophy." (PMID 33466232, 2021).
subacute sclerosing panencephalitis (1 paper, 2024). A chronic progressive encephalitis that develops a few years after measles infection and presents with a demyelination of the cerebral cortex. "Positive correlations were found between S100B and TNF-α, S100B and IL-1β, and NF-H and soluble TNF receptor 1 in subacute sclerosing panencephalitis." (PMID 39272777, 2024).
synovial sarcoma (1 paper, 2025). "The results indicate high expression levels of E-cadherin and cytokeratin 19 in epithelial cells and stronger reactions for vimentin and S100b in spindle cells of biphasic synovial sarcomas." (PMID 41155410, 2025).
teratocarcinoma (1 paper, 2016). A germ cell tumor characterized by the presence of an embryonal carcinoma component and a teratoma component. "Furthermore, RAGE, HMGB1, and S100B progressively increase during neuronal differentiation of teratocarcinoma-derived NT2/D1 cells: RAGE is expressed only in cells committed to a neuronal phenotype and directly involved in cellular morphological changes, and S100B seems to be the principal ligand." (PMID 27313835, 2016).
Thromboembolism (1 paper, 2018). The formation of a blood clot inside a blood vessel that subsequently travels through the blood stream from the site where it formed to another location in the body, generally leading to vascular occlusion at the distant site. "However, S100B has better sensitivity, negative predictive value and specificity than D-dimer, which is widely used in ruling out thromboembolism." (PMID 30458714, 2018).
thrombosis (1 paper, 2020). "After astragalus polysaccharide intervention treatment, the content of NSE and S-100β protein in cerebral thrombosis model rats was reduced, and after astragalus polysaccharide nanoparticle intervention treatment, the trend of NSE and S-100β protein decline was more obvious." (PMID 33425879, 2020).
thrombotic disorders (1 paper, 2025). "Circulating nucleic acids (CNAs), high-mobility group box 1 (HMGB1), von Willebrand factor (vWF), and S100b protein are notable markers of SI, indicative of tissue damage and implicated in thrombotic disorders." (PMID 41311551, 2025). "This SI is driven by factors like circulating nucleic acids (CNAs), S100b, high-mobility group box 1 (HMGB1), and von Willebrand factor (vWF), which reflect tissue damage and contribute to thrombotic disorders, including the formation of blood clots." (PMID 41311551, 2025).
thymoma (1 paper, 2014). A neoplasm arising from the epithelial cells of the thymus. "In a previous study S100β+ lymphocytes were found in 89% of thymomas." (PMID 24705787, 2014). "The degree of S100β+ lymphocyte infiltration correlated with thymoma stage." (PMID 24705787, 2014).
Tinnitus (1 paper, 2025). Tinnitus is an auditory perception that can be described as the experience of sound, in the ear or in the head, in the absence of external acoustic stimulation. "The top2 key proteins GFAP and S100B indicate the importance of astrocytes in the remodeling of the IC complex in tinnitus." (PMID 40076458, 2025). "The detection of GFAP and S100B as the top2 key proteins in tinnitus is unexpected." (PMID 40076458, 2025). "The database analysis carried out in the present study links changes in the interactions of BDNF-NTF3-NTRK3 in IC in tinnitus with altered interactions between astrocytes (GFAP, S100B) and neurons." (PMID 40076458, 2025).
uveitis (1 paper, 2015). An inflammatory process affecting a part of or the entire uvea. "Production of S100B during uveitis either by resident cells in the eye or by infiltrating cells is therefore likely to have up-regulated CCL22 and IL-1β in particular resulting in further recruitment of inflammatory cells and exacerbation of disease." (PMID 26204512, 2015).
ZIKV infection (1 paper, 2018). "Upon MR766 and PRVABC59 strains of ZIKV infection, the flavivirus antigen was localized to both S100B-positive and -negative cells in the cultures, indicating ZIKV infects astrocytes of different maturation stages." (PMID 29707233, 2018).